EGF (epidermal growth factor)
Diseases named in the same sentence as EGF in open-access papers (continued):
Sharing a sentence is not in itself a finding about the gene and the disease.
liver fibrosis (continued). "Epidermal growth factor (EGF) and its signaling molecules, EGFreceptor (EGFR) and signal transducer and activator of transcription factor 3 (STAT3), have been considered to play a role in liver fibrosis and cirrhosis." (PMID 26550019, 2015). "Although existing evidence supports the argument that treatment with individual EGF growth factors is sufficient to promote HSC activation at least in vitro, the in vivo requirement/redundancy for each one of these proteins in the development of liver fibrosis is not clear." (PMID 33520984, 2020).
Obesity (29 papers, 2014 to 2025). Accumulation of substantial excess body fat. "EGF has been linked to higher serum concentrations in patients with metabolic syndrome or obesity, indicating its potential as a biomarker." (PMID 40376303, 2025). "The data can be summarized as obesity-associated cytokines, including EGF, MCP1, MDC, MIP-1b, and Groα." (PMID 38541912, 2024). "Many of the common secreted upstream regulators we identified, such as TNF, IL-1β, IFN-γ, IL-18, CD40L, IL-6, EGF, TGFβ, and IL-21, were previously reported to be associated with obesity and metabolic dysfunction." (PMID 36880999, 2023). "Obesity-associated microenvironmental factors and other Src-activating growth factors, including the epidermal growth factor, activate Src and promote Src-mediated lipin-1 phosphorylation on Tyr398, Tyr413 and Tyr795 residues." (PMID 33203880, 2020). "EGFL6 expression, which encodes an epidermal growth factor found to be enhanced in obesity and alters insulin action, was increased by 8.5-fold." (PMID 32826922, 2020). "Obesity was associated with higher serum levels of EGF, Groα, MCP1, MIP-1b, MDC, VEGFα, and Leptin." (PMID 38541912, 2024). "In addition to these traditional laboratory parameters, LDH and EGF have emerged as novel obesity-related markers, pathophysiologically linked to obesity and insulin resistance, that deserve further attention." (PMID 24729662, 2014). "Future perspectives: Future studies should focus on evaluating the individual evolution of urinary EGF, renin and blood pressure under the influence of weight loss in children and adolescents with obesity, or the effect of physical exercise in both children and adolescents with obesity or T1DM." (PMID 36996194, 2023). "In obesity, hypertension is (at least partly) caused by salt-retention and associated with a low to normal renin production which in turn could trigger the kidney EGF production." (PMID 36996194, 2023). "Levels of IL-1RA and IFNγ were elevated with pregravid obesity, whereas GM-CSF and EGF concentrations were decreased." (PMID 39872537, 2024). "The obesity-associated cytokines, Groα, MDC, EGF, and MIP-1b, were significantly higher in AA than in LA." (PMID 38541912, 2024). "Both in boys with obesity as well as boys with T1DM the urinary EGF/urinary creatinine ratio is significantly correlated with the SBP and the MAP." (PMID 36996194, 2023). "In this study, we investigated the relation between urinary EGF, serum renin and blood pressure in children with obesity or T1DM." (PMID 36996194, 2023). "Some dysfunctional eating behaviors (frequent among persons with obesity) predicted concentrations of IL-10, EGF, IL-8 and IFN-γ." (PMID 31450770, 2019). "EGF serum levels have been described to inversely correlate with fat mass and BMI, supporting a role of EGF in the pathogenesis of obesity and related diseases." (PMID 28582461, 2017). "Moreover, the association between PP and MAP on the one hand and the excretion of urinary EGF in boys with either obesity or T1DM on the other hand, also represents a novel finding that has not been reported before, not even in adults." (PMID 36996194, 2023). "EGF and renin in vascular health children with either obesity or type 1 diabetes." (PMID 36996194, 2023). "Furthermore, decisions on further treatment such as metformin and appetite suppressant to manage obesity among PCOS women can be made based on the Hb-EGF expression levels." (PMID 36830813, 2023). "To investigate these hypotheses, a clinical study was set up in which we included children and adolescents with either T1DM or obesity, and analysed urinary EGF and serum renin in relation to blood pressure parameters." (PMID 36996194, 2023). "Aiming at dissecting a hypothetical interaction between systemic blood pressure, plasma renin and urinary EGF in children, we compared the characteristics of these three actors in two distinct paediatric populations, namely children with obesity and T1DM, thereby avoiding any overlap of disease." (PMID 36996194, 2023).
Obesity (continued). "Thus, this study aims to investigate the difference between endometrial Hb-EGF expression and hormonal changes in circulating blood in women with obesity and PCOS and women with normal BMIs and PCOS." (PMID 36830813, 2023). "Another study also indicates that elevation of EGF may play a role in the induction of obesity in mice after ovariectomy." (PMID 35956404, 2022). "We hypothesize that, while all BMI categories display a proportional reduction of EGF to limit ROS production, in severe obesity, GR activity increases to resist a more evident oxidative status." (PMID 28582461, 2017). "These molecular mechanisms are particularly important in insulin-resistant states, including obesity, in which the increase of EGF due to food restriction may trigger insulin-like compensatory mechanisms." (PMID 24729662, 2014). "So additionally to the known function of urinary EGF as an early prognostic biomarker for kidney damage, urinary EGF can also be considered as a sensitive alarm bell for preclinical undermined vascular health in obesity and T1DM at young age, long before the development of overt hypertension." (PMID 36996194, 2023). "Some genes are also affected by rare CNVs in subjects with obesity, and thereby, this drives an alteration in gene expression of epidermal growth factor EFEMP1, which is involved in ECM remodeling in SAT, indicating that rare CNVs could be involved in the development of early-onset obesity." (PMID 33803198, 2021). "Therefore, in the obesity-related cancer environment where many cytokines show altered profiles, angiogenesis factors (i.e., EGF, VEGF, and PAI-1) and inflammatory mediators (i.e., IL-1, IL-6, TNF-α, and leptin) are thought to cultivate a favorable environment for neoplastic cell growth." (PMID 26794215, 2016). "The patterns of serum FSH levels, LH/FSH ratios, DHEA levels and endometrial Hb-EGF expression were found to be altered in women with PCOS, especially those with obesity." (PMID 36830813, 2023). "The urinary EGF/urinary creatinine ratio is correlated with the SBP and the MAP in boys with obesity as well as in boys with T1DM." (PMID 36996194, 2023). "The third player in our study was urinary EGF/creatinine, which showed to be significantly lower in de T1DM group compared to the patients with obesity (p < 0.001 after correction for age, height z-score and sex)." (PMID 36996194, 2023). "EGF, MCP1, MDC, MIP-1b, and Groα were independent of T2D and HTN significantly associated with obesity." (PMID 38541912, 2024). "In our study population, a significant inverse correlation between MAP and urinary EGF was observed in the subgroup of boys with either T1DM or obesity, independent of eGFR." (PMID 36996194, 2023). "This is in line with several studies showing that obesity-related host signaling, including Insulin-like Growth Factor 1 (IGF-1), Epidermal Growth Factor (EGF) and IL pathways, may impact on CEBP-β expression and activity." (PMID 37447165, 2023). "Signaling pathways affected by gene dysregulation in the atopic group included angiopoietin signaling, epidermal growth factor signaling, AMP-activated protein kinase signaling, retinoid X receptor (RXR)/farnesoid X receptor (FXR) signaling, and leptin signaling in obesity." (PMID 33178726, 2020). "Thus, further in vitro and in vivo studies should be done to identify the mechanisms involved in the pathogenesis of PCOS and progesterone treatment, especially in the case of obesity, by focusing on the effects of FSH, LH/FSH and DHEA levels and Hb-EGF expression." (PMID 36830813, 2023). "Moreover, EGF and LDH may represent novel markers of obesity, which deserve further investigations." (PMID 24729662, 2014). "The inverse correlation between urinary EGF/creatinine and MAP in the male patients was confirmed in the multiple linear regression model, and appeared to be independent of disease (T1DM or obesity) and independent of eGFR." (PMID 36996194, 2023).
Obesity (continued). "Altogether, for the first time, IL-1α, IL-10, EGF, and IFN-γ were shown to differ between AN and HCs, and between AN and individuals with obesity with or without BED." (PMID 31450770, 2019). "Other signals such as EGF, BDNF, FGF, other growth factor signals, autonomic neuronal signals, myokines, muscle damage, pain and infection have been shown to affect insulin sensitivity partly or completely independent of obesity." (PMID 33544739, 2021).
brain tumor (28 papers, 2008 to 2025). "In brain tumor cell line U1242, C. edulis caused antiproliferation via epidermal growth factor (EGF) with IC50 of 1.74 μg/ml." (PMID 32908971, 2020). "For example, epidermal growth factor (EGF) peptide radiopharmaceuticals were found to be potential candidates for neuroimaging which are used for early detection of malignant gliomas or brain tumors." (PMID 25136634, 2014). "We performed a copy number variation (CNV) assay to assess the EGFR amplification status in 69 primary GBM (here defined as brain tumors, BT) and in corresponding neurospheres (here defined as NS), cultured in the presence of EGF and bFGF." (PMID 24330732, 2013). "Platelet-derived growth factor (PDGF) and epidermal growth factor (EGF) are ligands for tyrosine kinase receptors with crucial roles in brain tumor development." (PMID 22091432, 2011). "Operative samples of human GBM were obtained at the time of surgery, and brain tumor sphere cultures were established in NS-A basal medium plus epidermal growth factor (EGF) and basic fibroblast growth factor (bFGF) (EF medium)." (PMID 19067488, 2008). "Therefore, targeting brain tumors with EGF peptides facilitates the development of AuNPs that can cross the blood-brain barrier and lead to effective photodynamic tumor cell killing." (PMID 40809017, 2025). "Furthermore, applicability of anti-VEGF/EGF, as the multi-punitive strategy in therapy of brain tumor is required." (PMID 31565199, 2019). "We finally investigated the dynamic behavior of our cell lines cultured under differentiating (diff) conditions (medium supplemented with 10% FBS without FGF2 and EGF) that let them loss their stem cell properties including their capacity to generate brain tumors in immunodeficient mice." (PMID 33128011, 2020). "VEGF and EGF may be applied as the consistent biomarkers for brain neoplasms." (PMID 31565199, 2019). "Previous studies described that brain tumor stem cells (BTSCs), as well as their neural stem cell counterparts, are characterized by their ability to form neurospheres in defined serum-free culture medium supplemented with epidermal growth factor (EGF) and basic fibroblast growth factor (bFGF)." (PMID 18985161, 2008). "Additional enhancements included the attachment of an epidermal growth factor (EGF) peptide, which improved BBB penetration, resulting in higher and faster accumulation of these agents, specifically in brain tumor regions." (PMID 40661692, 2025). "Modern therapeutic approaches to brain tumors now aim to specifically target these biomolecules (VEGF, EGF, DKK...), thus attempting to slow down or stop the pathway underlying this protein." (PMID 37174040, 2023). "In addition, SPIONs were conjugated with recombinant human epidermal growth factor (SPION-EGF), and their efficiency in performing the MIR of malignant brain tumors overexpressing EGF receptors was evaluated." (PMID 36311203, 2022).
diabetic foot ulcers (28 papers, 2009 to 2025). "It has been reported that deficiency of epidermal growth factor (EGF) is one of the causes of diabetic foot ulcer (DFU)." (PMID 32726897, 2020). "A 2025 meta-analysis aimed to compare the therapeutic efficacy of various stem cell groups, PRP, and EGF in the treatment of diabetic foot ulcers (DFUs)." (PMID 40427966, 2025). "It is noteworthy that the optimum perilesional dose of EGF for treatment of diabetic foot ulcers is 1 μg/kg." (PMID 39808642, 2025). "EGF has been well documented for its positive role in wound healing, burns, diabetic foot ulcerations, many dermatological conditions and aesthetic applications." (PMID 39912963, 2025). "Both PRP and recombinant factors, such as PDGF and EGF, significantly enhance healing in diabetic foot ulcers." (PMID 41375885, 2025). "Recombinant human epidermal growth factor (EGF) has been used to treat adult diabetic foot ulcers and pediatric burns by facilitating wound healing and epithelization, especially for elderly patients." (PMID 35447848, 2022). "Regarding potential clinical translation, several growth factors, e.g., PDGF and recombinant human EGF, are used to treat diabetic foot ulcers by local injection into the wound sites, and several other growth factors are in clinical trials for wound healing." (PMID 34440733, 2021). "Topical imageplication of epidermal growth fctor (EGF) has been used to accelerate diabetic foot ulcers but with limited efficacy." (PMID 32276508, 2020). "Several studies evaluating the effects of EGF on diabetic foot ulcers concluded that treatment increases the incidence and rate of wound closure." (PMID 30993143, 2019). "Currently, the therapeutic use of local administration of growth factors such as EGF is under investigation in diabetic foot ulcers." (PMID 29592858, 2018). "Among the different therapeutic approaches that have been tested, the topical administration of EGF has been proposed as a promising agent, showing efficacy in the treatment of diabetic foot ulcers." (PMID 29592858, 2018). "In a compassionate study with terminal ulcer patients in 2001-2002, the first clinical evidence using EGF infiltration for diabetic foot ulcers and amputation residual bases emerged." (PMID 28904951, 2017). "After several exploratory and confirmatory clinical trials, the intralesional administration of human recombinant epidermal growth factor (hrEGF) has been approved for the treatment of advanced diabetic foot ulcers (DFU)." (PMID 24004460, 2013). "Clinically, EGF has proven effective in treating diabetic foot ulcers." (PMID 40182989, 2025). "Moreover, decreased expression of EGF has been reported in chronic wounds such as diabetic foot ulcers." (PMID 39808642, 2025). "The topical treatment of diabetic foot ulcers with EGF has also shown promising results." (PMID 38338748, 2024). "EGF is registered as a drug for diabetic foot ulcer treatment." (PMID 38338748, 2024). "Several EGF products with several formulae, such as intralesional injection, topical spray, dermal cream, and ointment, are commercially available to treat or alleviate diabetic foot ulcers (DFUs) and provide anti-aging skincare." (PMID 35447848, 2022). "In the present study, LWGA-SA coacervates encapsulating EGF were evaluated for in vitro activity in keratinocytes, in vivo wound healing efficacy in streptozotocin-induced diabetic mice, and storage stability, to evaluate their potential as a novel therapeutic modality for diabetic foot ulcers." (PMID 32276508, 2020). "In addition, rhEGF has been shown to enhance the healing of chronic diabetic foot ulcers, and we have observed that rhEGF increases the proliferation of human fibroblasts (unpublished observations), which suggest that EGF is effective in various types of wound healing." (PMID 19456848, 2009). "Epidermal growth factor (EGF) and basic fibroblast growth factor (b-FGF) can promote the proliferation of fibroblasts, so they could be used to treat diabetic foot." (PMID 36618858, 2022).
diabetic foot ulcers (continued). "Therefore, a comprehensive meta-analysis was performed to compare the efficacy and safety of epidermal growth factor (EGF) and placebo in healing diabetic foot ulcers." (PMID 37867626, 2022). "A prospective study reported that 21 of 89 patients showed improvement without EGF treatment, while complete healing of chronic diabetic foot ulcer was observed in 52 of 68 patients treated with EGF." (PMID 30993143, 2019).